FOS (Fos proto-oncogene, AP-1 transcription factor subunit)
Diseases named in the same sentence as FOS in open-access papers (continued):
Sharing a sentence is not in itself a finding about the gene and the disease.
infection (continued). "These master regulators include EGR1, FOS, SRF, and SP1, and could be interesting targets for future studies, since they could switch on several pathways targeting the genes that are important to the successful alleviation of HPAI infection." (PMID 35205087, 2022). "Notably, expression of the EGR1 and FOS transcription factors, which are known to be regulated by MAPK signaling pathways, was reduced in T3SS1+ΔvopQ-infected cells compared to T3SS1+-infected cells and highly elevated by T3SS1+ΔvopS infection (Data Set S1)." (PMID 33563785, 2021). "In addition, FOS and JUN were downregulated at this time point post-infection." (PMID 22455317, 2012). "Hence, our observations of increased FOS expression may not directly relate to pathogenesis during infection in vivo." (PMID 31664929, 2019). "This dataset displayed no significant increase in FOS, NR4A1 and FOSB gene expression (only a decrease at 48 hpi for FOSB) over the 96 h course of infection, like all other SARS‐CoV‐2 datasets." (PMID 38623540, 2024). "Since PCIF1 was not significantly changed at day 1 post-infection, suggesting that PCIF1 may not be the only factor affecting FOS and EGR1 expressions during HIV infection." (PMID 34545078, 2021).
cardiovascular disease (8 papers, 2015 to 2025). "FOS can be expressed in cardiomyocytes, endothelial cells, and vascular smooth muscle cells, and its expression level is closely associated with the development and progression of various cardiovascular disease." (PMID 40662135, 2025). "In cardiovascular diseases, FOS is activated after thrombin acts on endothelial cells and regulates the expression of VEGF, which plays a protective role in endothelial cells." (PMID 38818568, 2024). "The critical role of FOS has been investigated in several cardiovascular diseases." (PMID 38818568, 2024). "FOS regulates cell proliferation and migration and is upregulated in some cardiovascular diseases." (PMID 34858201, 2021). "Other seed genes, such as FOS, SOCS3 and MCL1, should also be mentioned due to their special clinical value in cardiovascular diseases." (PMID 34271875, 2021). "Other seed genes, such as FOS, SOCS3 and MCL1, may also be potential targets for treatment due to their special clinical value in cardiovascular diseases." (PMID 34271875, 2021).
hematological disease (7 papers, 2007 to 2024). "In this study, we have demonstrated the impairment of stress-induced FOS mRNA stabilization in MDS, which, to our knowledge, has not been reported in hematopoietic diseases before." (PMID 23593403, 2013).
bacterial infection (6 papers, 2013 to 2024). "Given the current antibiotic resistance crisis, we propose further in vivo investigation of FOS inhibitors in bacterial infections." (PMID 39261458, 2024). "However, whether FOS plays a role in the cell death caused by bacterial infections remains unknown." (PMID 39261458, 2024). "However, a more thorough investigation is needed to further consolidate the potential of FOS inhibitors as host-directed-therapeutics against bacterial infections." (PMID 39261458, 2024).
kidney diseases (5 papers, 2019 to 2024). "Notably, injured PT DARs were significantly enriched for NF1, HNF1B, and FOS motifs (NF1 P = 1.0 × 10−266; HNF1B P = 1.0 × 10−214; FOS P = 1.0 × 10−204), known regulators of PT identity, suggesting that epigenetic regulation may have implications for the development of kidney disease." (PMID 38287030, 2024). "Finally, the Nephroseq V5 tool was applied to identify the expression level of CCL2, FOS, JUN in kidney diseases, as well as the correlation between CCL2, FOS, JUN expression and renal function in the patients with IgAN." (PMID 35464092, 2022).
metabolic disorders (3 papers, 2024 to 2025). "First, what is the relationship among CDKN1A, FOS, ITGB4, and MAP2K1 in metabolic disorders after MI." (PMID 39069811, 2025).
retinopathy (3 papers, 2017 to 2024). "In summary, our study demonstrated that activation of the PGF2α/PTGFR axis accelerates experimental proliferative retinopathy through the secretion of ELR+ CXC chemokines via FOS‐mediated transcriptional regulation." (PMID 36511116, 2023). "An induction of FOS‐mediated ELR+ CXC chemokine expression was observed in retinal ECs from diabetic patients with proliferative retinopathy." (PMID 36511116, 2023).
heart disease (2 papers, 2014 to 2024). "To further understand the role of FOS, we also predicted the potential drugs for both capable of activating FOS and also treating heart diseases." (PMID 38517374, 2024).
immune disorder (2 papers, 2021 to 2023). "The present study proposed the hypothesis of the FOS involved mechanisms of UFs development which is anomalous DNA methylation and autophagy condition, even the concomitant immune disorder." (PMID 37138755, 2023).
infectious disease (2 papers, 2022 to 2023). A disorder directly resulting from the presence and activity of a microbial, viral, or parasitic agent in humans. "Recently, we showed in infectious disease research that T. cruzi dysregulates the expression profile of host piRNAs computationally predicted to target profibrotic molecules including TGFB1, FOS, and NFATC2 in primary human cardiac myocytes." (PMID 36936778, 2023).
peripheral neuropathy (2 papers, 2016 to 2021). A disorder affecting the peripheral nervous system. "For example, FOS, a commonly used marker of neuronal damage, was uniquely upregulated by oxaliplatin and thus could play a role in oxaliplatin-induced peripheral neuropathy." (PMID 34611476, 2021). "These include downregulation of histone genes by 5-FU (that significantly correlates with improved survival in CRC patients) and upregulation of FOS and ATF3 by oxaliplatin (which may contribute to peripheral neuropathy)." (PMID 34611476, 2021). "We observed downregulation of histone genes by 5-FU (that significantly correlates with improved survival in CRC patients) and upregulation of FOS and ATF3 by oxaliplatin (which may contribute to peripheral neuropathy)." (PMID 34611476, 2021).
intestinal disease (1 paper, 2025). "In future studies, we aim to further explore the specific roles of FOS in animals subjected to intestinal disease challenges, with the goal of uncovering deeper insights into its mechanisms of antioxidant activity, stress resistance, and intestinal health regulation." (PMID 40943613, 2025).
vasculopathy (1 paper, 2023). "In conclusion, exposure of HMECs to KTx-IgG from patients with allograft vasculopathy, but not KTx-IgG from patients without vasculopathy or healthy Con-IgG, triggers signaling through the PAR1-AP-1/c-FOS-miRNA-let7-axis, to control TNF-α gene transcription and TNF-α-induced monocyte activation." (PMID 37965310, 2023).
FOS also shares sentences with these, for which no sentence is quoted: osteopetrosis (43 papers); migraine (37); Arthritis (17); inflammation (8); multiple myeloma (8); oral cancer (7); Dyskinesia (6); status epilepticus (6); Tinnitus (6); Headache (5); neuroblastoma (5); neurodegenerative disease (5); oral squamous cell carcinoma (5); osteosclerosis (5); Seizure (5); acute myeloid leukemia (4); anxiety disorder (4); Cataplexy (4); chondrosarcoma (4); cognitive decline (4); fibrous dysplasia (4); gastritis (4); inflammatory bowel disease (4); metabolic dysfunction-associated steatohepatitis (4); myelodysplastic syndrome (4); neuropathy (4); alcoholism (3); bone cancer (3); dermatitis (3); endothelial dysfunction (3).
A further 235 diseases each share a sentence with FOS in 3 papers or fewer.